ANKRD36BP1 (ankyrin repeat domain 36B pseudogene 1)
Synonyms: MGC12538; formerly ANKRD26L1; ANKRD36BL1
Gene: Transcribed processed pseudogene on chromosome 1 (168,245,788 to 168,247,204, reverse strand). Ensembl gene ENSG00000214262.
Diseases named in the same sentence as ANKRD36BP1 in open-access papers:
ANKRD36BP1 is named in the same sentence as 1 disease in open-access papers, as found by Europe PMC text mining. Sharing a sentence is not in itself a finding about the gene and the disease. The quoted sentences say what the papers report.
tumor (2 papers, 2016 to 2023). "ANKRD36BP1 (dist = 3,795), TBX19 (dist = 29815) chr1:168220463A > I (p < 0.001), HOOK3 chr8:42883441A > I (p = 0.0011), PGPEP1 chr19:18476416A > I (p < 0.001), and NDUFV3 chr21:44329452A > I (p = 0.038) were significantly different between tumor and normal tissues." (PMID 36999050, 2023).